CPT1A (carnitine palmitoyltransferase 1A)
Description:
Catalyzes the transfer of the acyl group of long-chain fatty acid-CoA conjugates onto carnitine, an essential step for the mitochondrial uptake of long-chain fatty acids and their subsequent beta-oxidation in the mitochondrion. Also possesses a lysine succinyltransferase activity that can regulate enzymatic activity of substrate proteins such as ENO1 and metabolism independent of its classical carnitine O-palmitoyltransferase activity. Plays an important role in hepatic triglyceride metabolism (By similarity). Also plays a role in inducible regulatory T-cell (iTreg) differentiation once activated by butyryl-CoA that antagonizes malonyl-CoA-mediated CPT1A repression (By similarity). Sustains the IFN-I response by recruiting ZDHCC4 to palmitoylate MAVS at the mitochondria leading to MAVS stabilization and activation. Promotes ROS-induced oxidative stress in liver injury via modulation of NFE2L2 and NLRP3-mediated signaling pathways (By similarity).
Synonyms: CPT1-L; CPT I; CPTI-L; CPT1; L-CPT1
Tractability: Small molecule: a high-quality ligand is known; it belongs to a druggable protein family. Antibody: UniProt predicts a signal peptide or a membrane-spanning region. PROTAC: ubiquitination databases record sites on it; its protein half-life has been measured; a small molecule that binds it is known.
Target class: Enzyme; Transferase
Chemical probes: PD082159, PD083600, PD083813, PD083825, PD084823
Safety:
Unwanted effects reported when the protein is acted on. In parentheses: how it was acted on, where the effect was seen, and who reports it.
Increased, Liver Steatosis (inhibition; source: AOP-Wiki)
Gene: Protein-coding gene on chromosome 11 (68,754,620 to 68,844,410, reverse strand). Ensembl gene ENSG00000110090.
Subcellular location: Mitochondrion outer membrane
Subcellular location (Human Protein Atlas): Mitochondria
Pathways (Reactome):
Metabolism: Carnitine shuttle; PPARA activates gene expression
Circadian clock: RORA,B,C and NR1D1 (REV-ERBA) regulate gene expression
Gene Ontology:
Molecular function: carnitine O-palmitoyltransferase activity; protein-macromolecule adaptor activity; acyltransferase activity; identical protein binding
Biological process: carnitine metabolic process; epithelial cell differentiation; long-chain fatty acid metabolic process; positive regulation of innate immune response; carnitine shuttle; fatty acid beta-oxidation; fatty acid metabolic process; intracellular glucose homeostasis; cellular response to fatty acid; eating behavior; glucose metabolic process; liver regeneration; positive regulation of fatty acid beta-oxidation; regulation of fatty acid oxidation; regulation of insulin secretion; response to alkaloid; response to ethanol; response to hypoxia; response to nutrient; response to nutrient levels; response to tetrachloromethane; response to xenobiotic stimulus; triglyceride metabolic process
Cellular component: membrane; mitochondrial outer membrane; mitochondrion
Genetic constraint (gnomAD): Loss-of-function variants: 55 observed, 97.14 expected, observed/expected ratio (o/e) 0.57, 90% interval 0.46 to 0.71. The upper end of that interval is the gene's LOEUF score, 0.71, which puts it in group 2 of 6, group 1 being the genes least tolerant of losing a copy. Missense variants: 787 observed, 1,063.6 expected, observed/expected ratio (o/e) 0.74, 90% interval 0.7 to 0.79. Synonymous variants: 360 observed, 410.09 expected, observed/expected ratio (o/e) 0.88, 90% interval 0.81 to 0.96.
Gene-disease validity (ClinGen):
ClinGen rates the evidence that CPT1A causes each of these diseases.
carnitine palmitoyl transferase 1A deficiency (autosomal recessive): Definitive. Carnitine palmitoyltransferase 1A (CPT-1A) deficiency is an inborn error of metabolism that affects mitochondrial oxidation of long chain fatty acids (LCFA) in the liver and kidneys, and is characterized by recurrent attacks of fasting-induced hypoketotic hypoglycemia and risk of liver failure.
Homologues: Orthologues: chimpanzee CPT1A (99% identical), macaque CPT1A (92% identical), dog CPT1A (91% identical), pig CPT1A (89% identical), mouse Cpt1a (87% identical), rat Cpt1a (87% identical), guinea pig CPT1A (84% identical), tropical clawed frog cpt1a (82% identical), zebrafish cpt1ab (71% identical), zebrafish cpt1aa (70% identical), Drosophila melanogaster whd (50% identical), Caenorhabditis elegans cpt-1 (47% identical), and 1 more. Paralogues in human: CPT1B (62% identical), CPT1C (55% identical), CHAT (26% identical), CRAT (26% identical), CPT2 (24% identical), CROT (23% identical).
Diseases named in the same sentence as CPT1A in open-access papers:
CPT1A is named in the same sentence as 236 diseases in open-access papers, as found by Europe PMC text mining. Sharing a sentence is not in itself a finding about the gene and the disease. The quoted sentences say what the papers report.
breast cancer (72 papers, 2010 to 2026). A primary or metastatic malignant neoplasm involving the breast. "Expression of CPT1A was elevated in breast cancer, which was frequently linked to an advanced progression and a worse prognosis." (PMID 41444950, 2025). "Although high CPT1A expression is correlates with poor outcome in breast cancer patients, the molecular mechanism underlying this correlation remains elusive." (PMID 39097623, 2024). "Elevated expression of Cpt1a is associated with genetic mutations, metabolic disorders, and cancers, such as breast cancer due to its lipid-rich environment." (PMID 39097623, 2024). "In this study, through combining different datasets derived from two separate cohorts of ER+ breast cancer patients, we show that higher expression of CPT1A is associated with worse prognosis." (PMID 37207154, 2023). "CPT1A is a rate-limiting enzyme in fatty acid oxidation and is upregulated in high-risk breast cancer." (PMID 36735704, 2023). "Taken together, these analyses using open-access databases bolster the potential role of CPT1A-dependent fatty acid metabolism as a pathogenic factor in breast cancer." (PMID 36735704, 2023). "The connection between CPT1A mutations and breast cancer outcome is a gap in the literature, and this study explores the trend and the possible mechanisms behind it." (PMID 36735704, 2023). "CPT1 is a rate-limiting enzyme of FAO, whose isozyme CPT1A deficiency inhibits the invasion and growth of radiotherapy-resistant breast cancer by reducing FAO." (PMID 35896782, 2022). "This is supported by the finding that clustering of CPT-1A with immune-related pathways in the context of under expression identified histological subtypes of breast carcinoma which are associated with a favourable prognosis." (PMID 36180554, 2022). "CPT-1A genomic alterations were detected in 9% of breast carcinomas, and are associated with a poor prognosis, as is the metagene associated with CPT-1A alterations." (PMID 36180554, 2022). "Although CPT-1A genomic alterations are detected in 9% of breast carcinomas, both the alteration and the metagene associated with it, confers a poor prognosis." (PMID 36180554, 2022). "In the present study, we investigated the potential of CPT1A to serve as a diagnostic biomarker for breast cancer." (PMID 33858374, 2021). "Our large-scale study provided initial data about the clinically diagnostic relevance of CPT1A as a serum marker for breast cancer in both a training set and a test set." (PMID 33858374, 2021). "Serum CPT1A levels were higher in breast cancer patients than in controls and were significantly associated with metastasis, TNM stage, histological grading and molecular subtype." (PMID 33858374, 2021). "ROC curves based on the ELISA results in the training set and test set were plotted to determine the diagnostic efficiency of serum CPT1A in breast cancer." (PMID 33858374, 2021). "According to the binary logistic regression analysis in the training set, diagnostic models of CPT1A for breast cancer diagnosis were constructed." (PMID 33858374, 2021). "Then, we measured the serum levels of CPT1A in a large-scale study and evaluate its clinical significance and diagnostic efficiency for breast cancer." (PMID 33858374, 2021). "CPT1A/CPT2 were highly expressed in recurrent human breast cancers and are associated with poor prognosis." (PMID 33123488, 2020). "Data from TCGA clearly confirm a CPT1A association with poor prognosis in breast cancer, whereas CPT1A is a marker of good prognosis in renal cancer and CPT1C in pancreas." (PMID 33194695, 2020). "Enhanced CPT1A/CPT2 expression was detected in the recurrent human breast cancers and associated with a worse prognosis in breast cancer patients." (PMID 31803610, 2019). "Since low FAO signature expression in breast tumours was associated with poor outcome, we investigated the effect of CPT1A overexpression in a breast cancer cell line." (PMID 30092766, 2018).
breast cancer (continued). "CPT1B is expressed in muscle, heart, and adipose tissue and CPT1C in neurons, whereas CPT1A is more widely expressed and has been previously implicated as a therapeutic target in breast cancer cells." (PMID 29596410, 2018). "While increased CPT1A expression in ER+ breast cancer patients was associated with a significant decrease in overall survival, no data are available on obesity and other metabolic health parameters in this patient population." (PMID 28101337, 2017). "CPT1A deficiency could repress the aggressive growth and radioresistance of breast cancers by blocking FAO." (PMID 41444950, 2025). "Collectively, these results indicate that Cpt1a-deficient cells rely on Nrf2 to promote glucose consumption, revealing a metabolic vulnerability that can be exploited by pharmacological or genetic targeting of these pathways in breast cancers." (PMID 39097623, 2024). "In 1214 patients, higher CPT1A expression is associated with lower breast cancer survivability." (PMID 36735704, 2023). "CPT1A is upregulated in breast cancer, worsening prognoses for high-risk patients." (PMID 36735704, 2023). "CPT-1A’s interactions with cancer pathways is far wider than previously realised and includes associations with epigenetic regulation and immune evasion pathways, as well as wild-type moderate to high penetrant genes involved in hereditary breast cancer." (PMID 36180554, 2022). "Moreover, univariate logistic regression analysis also revealed that CPT1A was an effective diagnostic factor independently of the lipids in differentiating breast cancer patients from healthy controls." (PMID 33858374, 2021). "Serum CPT1A displayed a remarkably high diagnostic efficiency for breast cancer and could be a novel biomarker for the diagnosis of breast cancer." (PMID 33858374, 2021). "In our study, univariate logistic regression analysis showed that none of the lipids TG, TC, HDL-C, LDL-C, or NEFA was an effective diagnostic indicator in breast cancer patients overall, and serum CPT1A showed significant effectiveness in breast cancer diagnosis independently of these lipids." (PMID 33858374, 2021). "Serum CPT1A is positively associated with breast cancer progression and could serve as an indicator for disease monitoring." (PMID 33858374, 2021). "Among breast cancer patients, low CPT1A expression correlates with poor survival when CD8+ T cell infiltration is high." (PMID 42146389, 2026). "For instance, overexpression of CPT1A has been observed in prostate cancer, colorectal cancer, breast cancer, and glioblastoma." (PMID 40867868, 2025). "Other research suggested CPT1A as one of the eight growth-dependent genes in the luminal subtype of breast cancer." (PMID 40002245, 2025). "CPT1A facilitates glutamine-independent growth of breast cancer cells by increasing the global lysine succinylation status in cells, especially the succinylation of enolase 1 at K80/81 and K335, which inhibits enolase activity." (PMID 40865948, 2025). "In breast cancer (BRCA_GSE148673), 10 cell populations were identified to express CPT1A, with predominant expression in endothelial, epithelial, and proliferating T cells." (PMID 41219902, 2025). "Experiments proved that CPT1A acts as an LSTase to inhibit enolase 1 enzyme activity and promote the proliferation of breast cancer cells under glutamine starvation." (PMID 40865948, 2025). "Breast cancer cells depend on CPT1A for FAO and, in turn, activate NF-κB signaling in a lysine acetyltransferase 2a-dependent manner through p65 acetylation, conferring metastatic characteristics." (PMID 41219902, 2025). "MiR-107 regulates the expression of CPT1A by targeting, thereby modulating breast cancer growth and metastasis." (PMID 40016582, 2025). "Altogether, these results suggested that RACGAP1 silencing sensitizes breast cancer ferroptosis by regulating CPT1A-dependent FA metabolism." (PMID 41444950, 2025).
breast cancer (continued). "ACSL4 not only promotes the intracellular lipogenesis and lipid droplets accumulation but also enhances fatty acid oxidation and adenosine triphosphate production by upregulating CPT1A to drive breast cancer metastasis." (PMID 40050614, 2025). "Taken together, these data confirm that ErbB2+ breast cancer cells rely on the uptake and oxidation of FAs for energy production and argue that, of the three isoforms of Cpt1, Cpt1a is primarily responsible for regulating FAO in this context." (PMID 39097623, 2024). "Supporting this, a recent study has shown that FDXR drives the proliferation of primary and endocrine-resistant breast cancer cells by promoting mitochondrial fatty acid oxidation through CPT1A upregulation." (PMID 39367275, 2024). "In clinical samples, USP10 levels correlated with IGF2BP1 and CPT1A levels, and breast cancer patients with high levels of USP10, IGF2BP1, and CPT1A had the worst outcome." (PMID 36632454, 2023). "Invasion and lymphangiogenesis in breast cancer cells can be inhibited by CPT1A knockdown, and CPT1A-null Human Dermal Lymphatic Endothelial Cells (HDLEC cells) consistently showed impaired invasion and lymphangiogenesis." (PMID 37033619, 2023). "Beyond breast cancer, matrix detached colorectal and ovarian cancer cells accumulate ROS upon CPT1a silencing 57 and oxidize oleate to sustain mitochondrial respiration 58, respectively." (PMID 36732635, 2023). "This study adds a new perspective to an established trend by breaking down the analysis of CPT1A and breast cancer by obesity and menopausal status." (PMID 36735704, 2023). "To corroborate the image analysis results, we further explore the relationship between CPT1A and breast cancer, through the lens of the relationship between CPT1A and obesity." (PMID 36735704, 2023). "CPT1A is upregulated in breast cancer, and inhibiting CPT1A activates cell apoptosis and suppresses cancer cell invasion." (PMID 36735704, 2023). "When co-cultured with breast cancer cells, the consumption of TAGs within adipocytes is increased, which in turn transfers adipocyte-derived FFAs to breast cancer cells, increasing CPT1A levels and driving FA metabolism in cancer cells." (PMID 37700339, 2023). "The MiR-328-3p-CPT1A-FAO pathway is crucial for the metastasis of breast cancer, and miR-328-3p upregulation can be used for reducing metastasis in breast cancer patients." (PMID 37033619, 2023). "Pre-menopausal breast cancer patients with a high expression level of CPT1A had a higher survival rate than their post-menopausal counterparts until the two groups’ intersection at 3663 days." (PMID 36735704, 2023). "CPT1A can modulate the succinylation of enolase 1 to enhance the growth of breast cancer and the succinylation of S100A10 to facilitate the spread of gastric cancer." (PMID 37033619, 2023). "In an earlier study, CPT-1A was shown to be a novel biomarker for the diagnosis and prediction of breast cancer." (PMID 37251324, 2023). "MiR-328-3p CPT1A is a downstream target of miR-328-3p in breast cancer, and miR-328-3p overexpression suppresses cancer spread by interfering with FAO via CPT1A." (PMID 37033619, 2023). "We further show that breast cancer cells rely on CPT1a for fatty acid oxidation, which in turn activates NF-κB signaling via the acetylation of p65 in a KAT2a-dependent manner." (PMID 36732635, 2023). "Mechanistically, breast cancer cells use palmitate to synthesize acetyl-CoA in a carnitine palmitoyltransferase 1a (CPT1a)-dependent manner." (PMID 36732635, 2023). "We proposed that ACSL4 promotes FAO and ATP production by upregulating CPT1A, thereby providing energy support for breast cancer metastasis." (PMID 38078907, 2023). "We utilized RNA sequencing data in the Xena Functional Genomics Explorer, to explore CPT1A’s effect on breast cancer patients’ survival probability." (PMID 36735704, 2023).